PTPN1 (protein tyrosine phosphatase non-receptor type 1)
Diseases named in the same sentence as PTPN1 in open-access papers (continued):
Sharing a sentence is not in itself a finding about the gene and the disease.
tumor (continued). "NB tumor samples from 44 patients were analysed by immunohistochemistry using specific antibodies against PTPN1, PTPRH, PTPRZ1, and PTEN." (PMID 31837707, 2019). "The role of PTPN1 in cancer is controversial, as it has been shown to act as both a tumor suppressor and a tumor promoter." (PMID 31527306, 2019). "In this study, analysing human NB tumor samples and cell lines, we have found evidence for PTPN1 as a regulator of NB cell tyrosine phosphorylation and proliferation, and unveiled the association of PTPN1 expression with poor NB patient outcome." (PMID 31837707, 2019). "In contrast, PTPN1 is as a tumor promoter in colorectal, non-small cell lung, breast, gastric, and colon cancer." (PMID 31527306, 2019). "The expression patterns of PTPN1 in human NB cells and NB tumor samples was investigated, in comparison with other PTPs, including PTPRH, PTPRZ1, and PTEN." (PMID 31837707, 2019). "Here, we found that PTPN1 was a tumor promoter, and its expression increased in HCC tissues and cell lines." (PMID 31527306, 2019). "The link between the IGF1R‐PTPN1 proteins is known: literature data indicate a crucial role of PTPN1 as a tumour suppressor, able to negatively regulate multiple pathways of cell growth directly through IGF1R and IR, or indirectly through leptin receptor GHR." (PMID 29577582, 2018). "Further, linc00673 reportedly acted as a tumor suppressor through regulation of the protein tyrosine phosphatase PTPN1." (PMID 28423732, 2017). "Our group also used a specific PTPN1 inhibitor that protected the mmtv-neu transgenic mice from developing tumours to confirm those findings." (PMID 18317580, 2008). "Expression was also detected in non-immune compartments,including epithelial (28.6%), stromal (21.5%) and mast cells (12.3%).Statistical comparison between tumor and normal compartments showedno significant differences in PTPN1 expression acrossmajor immune cell populations." (PMID 41432362, 2026). "In addition, recent studies have shown that increased PTPN1 is involved in tumour immunity and promotes tumour growth." (PMID 39289804, 2024). "Thus, we furthermore analyzed the correlation of PTPN1 expression with immune checkpoints and tumor infiltrated immune cells, respectively." (PMID 36741874, 2023). "Phosphosites from immune system-associated proteins (e.g., IL3RA, PECAM1, PTPN1, SIGLEC7, and JUP) showed an overall higher phosphorylation in tumor tissues than in normal adjacent tissues, suggesting enhanced immune signaling is likely to occur during tumor development." (PMID 33953186, 2021). "CAPN1 enhances the malignant behavior and erlotinib resistance of LUAD cells via degrading PTPN1 and then activating c‐Met/PIK3R2, which suggests CAPN1/PTPN1 may serve as tumor markers or potential targets for diagnosis and treatment of LUAD." (PMID 32395869, 2020). "Thus, PTPN1 knockdown would be expected to inhibit carcinogenesis and reduce tumor cell proliferation." (PMID 26755347, 2016). "Furthermore, all affected probands in this study presented a deletion, consistent with a tumor suppressing function of oncogenic kinases, and PTPN1 has been shown to be able to play both a pro- and anti-oncogenic role." (PMID 23372565, 2013). "PTPN1 may exert tumor suppressing or tumor promoting effects depending on the substrate involved and the cellular context." (PMID 21144060, 2010). "As tumor cells and trophoblasts exhibit many similarities and we observed miR-135a-5p overexpression to inhibit PTPN1 expression within HTR-8/SVneo, we hypothesize that miR-135a-5p may impair proliferative, invasive, and migratory activity of trophoblasts via PTPN1." (PMID 35610725, 2022). "We demonstrate that genetic silencing or pharmacological dual inhibition of protein tyrosine phosphatases PTPN1 and PTPN2 (PTPN1/N2) in NK cells significantly enhances anti-tumor cytolytic activity both in vitro and in vivo." (PMID 41986797, 2026).
tumor (continued). "Tumor sequencing revealed LOH in CHEK2 and PALB2, as well as CCND1,FGFR1, GPR124, ZNF217, ZNF703, and PTPN1 amplifications." (PMID 38091153, 2024). "Previous results have indicated that the expression of PTPN1 was elevated in intratumoral CD8+ T cells, which inhibits the anti-tumor immunity of CD8+ T cells." (PMID 37936713, 2023). "SETD1A knockdown changed the landscape of SEs, resulting in activation of the transcription of SE-driven tumor suppressors, such as ST3GAL4, AKAP12, PTPN1, AQP9, and ANKRD11." (PMID 37581938, 2023). "Tumor cells, B cells, T cells, macrophages, and NK cells were identified in GSE146115, and PTPN1 was enriched in T cells." (PMID 36741874, 2023). "PTPN1 and PTPN2 inhibitors have been developed and have become emerging means to enhance T cell anti-tumor immunity." (PMID 37884566, 2023). "Four of these intersecting genes, including PTPN1, CHSY1, SIAH1, and CCSAP, were correlated with tumor cell proliferation, migration, and invasion, and we therefore further confirmed their expression levels via RT-qPCR." (PMID 35610725, 2022). "Leukocyte-derived chemotoxin 2 (LECT2), a tumor suppressor in HCC, contributes to blocking vascular invasion and metastasis in HCC by recruiting PTPN1 to antagonize MET receptor activation." (PMID 35957898, 2022). "IL6R, PLCG1, PTPN1, and HCK are involved in cytokine/interferon signaling to activate immune cells to counter proliferating tumor cells." (PMID 30978274, 2019). "They found that the rate of tumor development, number of tumors and lung metastases were significantly reduced in NDL2 transgenic mice both in PTPN1-/- mice and in PTP1B inhibitor treated mice." (PMID 28855549, 2017). "Previous studies reported that several PTPs such as PTPN1, PTPN3, and PTPN6 have oncogenic properties but other PTPs including PTPN12 have tumor suppressor features." (PMID 22394684, 2012). "In addition, the protein tyrosine phosphatase (PTPN1) and cyclooxygenase‐2 (COX‐2) are central regulators of inflammation, and their downregulation in immune cells promotes anti‐tumor immunity." (PMID 39840604, 2025). "Thus, treatment of tumour cells with AC484 phenocopies the effects of deletion of both Ptpn2 and Ptpn1 on cell growth and ISG expression in response to IFN, and enhances tumour sensitivity to T cell-mediated toxicity." (PMID 37794185, 2023). "The results revealed that PTPN1 expression was significantly higher in tumor tissues than in matched non-tumor adjacent tissues and that PTPN1 was localized in the cytoplasm." (PMID 37936713, 2023). "In addition, SOX2 has been shown to activate the JAK-STAT pathway, which regulates both immune response and tumor progression, while inhibiting SOCS3 and PTPN1, which are regulators of immune signaling." (PMID 34831420, 2021). "Here, we have investigated the function and expression of the non-receptor PTPN1 on human NB cell lines and human NB tumor samples." (PMID 31837707, 2019). "The aneuploidic increases in copy number of genes that may promote tumor formation, including ARHGAP26, GRB10, DDHD2, FGFR1, CTNNA3, PTPN1 and MLLT1 in the apparently stable and karyotypically normal lines HS293 and HS401, are cause for concern." (PMID 20428235, 2010). "We analyzed the expression levels of PTPNs in the TCGA database and discovered that PTPN1, PTPN6, PTPN7, PTPN18, PTPN20, and PTPN22 were significantly upregulated in tumor samples, while PTPN4, PTPN5, PTPN10, PTPN11, PTPN13, PTPN14, and PTPN21 were downregulated in tumor samples." (PMID 36226189, 2022).
tumor (continued). "Furthermore, deletion of PTPN1 and PTPN2 in DCs stimulated the growth of IL-12 and IFN-γ, which amplified the IL-12/STAT4/IFN-γ/STAT1/IL-12 positive autocrine loop, boosting the therapeutic potential of mature monocyte-derived dendritic cells (moDCs) in tumor-bearing mice." (PMID 35957898, 2022). "Upstream, RNF213 is negatively regulated by Protein tyrosine phosphatase 1B (PTP1B or PTPN1) and this was found to be important for hypoxia sensing and control of non-mitochondrial oxygen consumption in tumours." (PMID 34804992, 2021). "Until now, no studies have reported the role of PTP1B in PDAC proliferation and progression, although both a tumor suppressor and an oncogene function of PTPN1 have been proposed." (PMID 31745071, 2019).
infection (19 papers, 2011 to 2025). The state of being infected such as from the introduction of a foreign agent such as serum, vaccine, antigenic substance or organism. "It is thus possible that PTPN1 and UPR genes have different expressions and kinetics depending on the kind of infection but, given the limited number of patients, it did not appear reasonable to compare patients according to their infectious source." (PMID 31737637, 2019).
animal disease (1 paper, 2023). "Whether PTPN1 deficiency protects or exacerbates lung remodeling is likely dependent on the context and animal disease model." (PMID 36672250, 2023).
PTPN1 also shares sentences with these, for which no sentence is quoted: cardiovascular disease (12 papers); liver diseases (9); Glucose intolerance (8); heart failure (8); liver fibrosis (8); neurodegenerative disease (7); neurological disorders (7); triple-negative breast carcinoma (6); colitis (5); diabetic retinopathy (5); Hyperinsulinemia (5); infectious disease (5); renal cell carcinoma (5); type 1 diabetes (5); Anxiety (4); autoimmune disease (4); B Cell Lymphoma (4); Hypoglycemia (4); inflammation (4); acute myeloid leukemia (3); Cerebral ischemia (3); chronic heart failure (3); epidermoid carcinoma (3); insulinoma (3); myocardial infarction (3); osteosarcoma (3); Parkinson disease (3); acute promyelocytic leukemia (2); bacterial infections (2); Bladder Tumor (2).
A further 129 diseases each share a sentence with PTPN1 in 2 papers or fewer.